MICU2 (mitochondrial calcium uptake 2)
Description:
Calcium sensor of the mitochondrial calcium uniporter (MCU) channel, which senses calcium level via its EF-hand domains. MICU1 and MICU2 form a disulfide-linked heterodimer that stimulates and inhibits MCU activity, depending on the concentration of calcium. At low calcium levels, MICU1 occludes the pore of the MCU channel, preventing mitochondrial calcium uptake. At higher calcium levels, calcium-binding to MICU1 and MICU2 induces a conformational change that weakens MCU-MICU1 interactions and moves the MICU1-MICU2 heterodimer away from the pore, allowing calcium permeation through the MCU channel.
Synonyms: hMICU3; EFHA1; 1110008L20Rik
Tractability: Small molecule: a structure with a bound ligand is known. PROTAC: ubiquitination databases record sites on it; its protein half-life has been measured.
Gene: Protein-coding gene on chromosome 13 (21,492,691 to 21,604,181, reverse strand). Ensembl gene ENSG00000165487.
Subcellular location: Mitochondrion intermembrane space; Mitochondrion inner membrane
Subcellular location (Human Protein Atlas): Nucleoplasm; Mitochondria
Pathways (Reactome):
Transport of small molecules: Mitochondrial calcium ion transport; Processing of SMDT1
Metabolism of proteins: Mitochondrial protein degradation
Gene Ontology:
Molecular function: calcium ion binding; calcium ion sensor activity; protein binding; protein heterodimerization activity
Biological process: calcium import into the mitochondrion; cellular response to calcium ion; mitochondrial calcium ion homeostasis; mitochondrial calcium ion transmembrane transport; negative regulation of mitochondrial calcium ion concentration; positive regulation of mitochondrial calcium ion concentration
Cellular component: mitochondrial inner membrane; mitochondrial intermembrane space; mitochondrion; uniplex complex; calcium channel complex
Genetic constraint (gnomAD): Loss-of-function variants: 36 observed, 35.12 expected, observed/expected ratio (o/e) 1.02, 90% interval 0.79 to 1.35. The upper end of that interval is the gene's LOEUF score, 1.35, which puts it in group 5 of 6, group 1 being the genes least tolerant of losing a copy. Missense variants: 407 observed, 381.42 expected, observed/expected ratio (o/e) 1.07, 90% interval 0.98 to 1.16. Synonymous variants: 155 observed, 136.22 expected, observed/expected ratio (o/e) 1.14, 90% interval 1 to 1.3.
Gene-disease validity (ClinGen):
ClinGen rates the evidence that MICU2 causes each of these diseases.
mitochondrial disease (autosomal recessive): Limited.
Homologues: Orthologues: chimpanzee MICU2 (99% identical), macaque MICU2 (95% identical), mouse Micu2 (86% identical), rat Micu2 (85% identical), guinea pig MICU2 (85% identical), dog MICU2 (84% identical), rabbit MICU2 (83% identical), pig MICU2 (82% identical), tropical clawed frog zdhhc20 (61% identical), zebrafish micu2 (34% identical), Caenorhabditis elegans C56A3.6 (29% identical). Paralogues in human: MICU3 (39% identical), MICU1 (23% identical).
Diseases named in the same sentence as MICU2 in open-access papers:
MICU2 is named in the same sentence as 29 diseases in open-access papers, as found by Europe PMC text mining. Sharing a sentence is not in itself a finding about the gene and the disease. The quoted sentences say what the papers report.
cardiac hypertrophy (2 papers, 2020). "Meanwhile, we also measured mitochondrial MICU2 expression in cardiac hypertrophy." (PMID 33259334, 2020). "Furthermore, the expression of the MCUC regulatory subunit MICU2 is altered in patients with ventricular hypertrophy, and MICU2-KO mice display diastolic dysfunction, possibly associated with delayed cytosolic Ca2+ re-uptake and decreased cardiomyocyte relaxation." (PMID 32671075, 2020).
cognitive deficits (2 papers, 2020 to 2023). "Variants in the MICU2 gene have been shown to give rise to severe cognitive impairment, spasticity, and white matter changes." (PMID 33426505, 2020). "Unlike MICU1 deficiency, MICU2 truncation produces cognitive deficits without motor involvement." (PMID 37484823, 2023).
abdominal aortic aneurysm (1 paper, 2021). Enlargement and ballooning of the vessel that supplies arterial blood to the abdomen, pelvis and legs. "They showed that naive Micu2−/− mice could develop abdominal aortic aneurysms with spontaneous rupture with modest blood pressure elevation and concluded Micu2 is crucial in protecting the abdominal aorta." (PMID 33407182, 2021).
breast carcinoma (1 paper, 2024). "We analyzed protein levels in biopsies from four randomly selected patients, revealing a substantial increase in MiCU1 protein levels across various breast cancer samples, while MiCU2 expression showed a lower abundance compared to MiCU1." (PMID 38911376, 2024). "Furthermore, in the case of MiCU2, we screened 438 drugs, identifying 12 with inhibitory effects and 2 that can promote MiCU2 expression in breast cancer cells." (PMID 38911376, 2024). "While previous studies have established the link between MiCU1/2 cancer, this research aims to comprehensively assess both MiCU1 and MiCU2 in the breast cancer tumor microenvironment, particularly focusing on their influence on immune cell regulation, which remains poorly understood." (PMID 38911376, 2024). "Conversely, AS601245 and WIKI4 were found to promote MiCU2 expression in breast cancer cells." (PMID 38911376, 2024).
colon adenocarcinoma (1 paper, 2024). "In particular, using The Cancer Genome Atlas Colon Adenocarcinoma (TCGA-COAD) data set, the authors observed that the expression of MICU1 and MICU2 are respectively down- and up-regulated with stages." (PMID 39466877, 2024).
colon cancer (1 paper, 2024). "MICU2 is crucial for the migration of colon cancer cells and metastatic spread to the liver." (PMID 39466877, 2024).
colon tumors (1 paper, 2024). "Here, we focused on investigating the expression of MICU1, MICU2, and the MICU2/MICU1 ratio in colon tumors using the cohort published by TCGA." (PMID 39466877, 2024). "We found that MICU2 expression is significantly up-regulated in colon tumors of patients with stage IV CRC." (PMID 39466877, 2024). "Interestingly, the MICU2/MICU1 ratio is significantly up-regulated in colon tumors of stage IV compared with tumors belonging to less aggressive stages." (PMID 39466877, 2024).
colorectal cancer (1 paper, 2024). A primary or metastatic malignant neoplasm that affects the colon or rectum. "Here, we describe the role of MICU2 in cell proliferation and invasion using in vitro and in vivo models of human colorectal cancer (CRC)." (PMID 39466877, 2024).
developmental disability (1 paper, 2020). Disorders in which there is a delay in development based on that expected for a given age level or stage of development. "Genetic variations in MICU1 and MICU2 have been reported to cause myopathy, developmental disability and neurological symptoms typical of mitochondrial disorders." (PMID 32395406, 2020).
hepatocellular carcinoma (1 paper, 2024). A malignant tumor that arises from hepatocytes. "In hepatocellular carcinoma (HCC), studies have demonstrated that patients exhibiting high expression of MCU/MiCU2 have a poorer prognosis in terms of overall survival (OS)." (PMID 38911376, 2024).
insulinoma (1 paper, 2021). "EndoC-βH1 cells behaved similarly to rodent insulinoma cells, in which the maximal [Ca2+]mito elevation following depolarization with 50 mM of KCl was diminished by 90% in MICU2-silenced cells (p < 0.0001)." (PMID 33932586, 2021). "To understand the role of MICU2 in stimulus-secretion coupling in pancreatic β cells, we silenced MICU2 in INS-1 832/13 cells, a rodent-derived insulinoma cell line, and in EndoC-βH1 cells, a human embryonic insulin-secreting cell line." (PMID 33932586, 2021).
liver cancer (1 paper, 2020). An epithelial or non-epithelial malignant neoplasm that arises from the liver. "Analysis of the array expression database revealed that CREB1 has a strong binding site in the upstream promoter region of MCU and MICU2 in liver cancer (HepG2) cells." (PMID 33114428, 2020). "The mRNA levels of CREB, MCU, MICU1, and MICU2 were found to be significantly increased in liver cancer, indicating that these proteins may have potential carcinogenic effects." (PMID 33114428, 2020). "Next, we analyzed the endogenous levels of CREB, MCU, MICU1, and MICU2 in liver cancer cells and normal liver cell lines, and the results showed that the mRNA expression levels of CREB, MCU, MICU1, and MICU2 in liver cancer cell lines were higher than that in normal liver cells." (PMID 33114428, 2020). "In addition, it does not affect the MICU2 levels, but it affects the mitochondrial Ca2+ uptake after the MICU1 gene is knocked down or overexpressed in liver cancer cells." (PMID 33114428, 2020).
MELAS (1 paper, 2022). "The PTCD3 (related to mitochondrial translation) and MICU2 (a mitochondrial inner membrane protein) were not expressed at all in MELAS patients." (PMID 36254078, 2022).
Retinal dystrophy (1 paper, 2023). Retinal dystrophy is an abnormality of the retina associated with a hereditary process. "Additional examples include the animal models of MICU2 and AGBL5 deficiency identified, respectively, in family F5563 with severe neurodevelopmental disorder and family F2707 with non-syndromic retinal dystrophy." (PMID 37644014, 2023).
neurodevelopmental disorder (3 papers, 2020 to 2023). A behavioral and cognitive disorder with onset during the developmental period that involves impaired or aberrant development of intellectual, motor, or social functions. "In the nervous system, invalid mutations in the MICU2 gene lead to abnormal mitochondrial calcium homeostasis and severe neurodevelopmental disorders." (PMID 33046081, 2020).
tumor (3 papers, 2019 to 2024). "Furthermore, MICU2 is the only component significantly associated with vascular invasion and showed a trend towards association with the presence of distant tumor metastases (P = 0.077)." (PMID 39466877, 2024). "Using western blotting, we compared the protein expression of MCU, MICU1, and MICU2 in a non-tumor colorectal epithelial cell line, NCM356, and in 5 CRC cell lines (HT29, DLD1, SW480, HCT116, and SW620) with different mutation and aggressiveness profiles." (PMID 39466877, 2024). "Interestingly, MICU2 expression was significantly higher in the more aggressive tumor cell lines (SW480, HCT116, and SW620) compared with the less aggressive cell lines (HT29 and DLD1) and the non-tumor cell line (NCM356)." (PMID 39466877, 2024). "Given the established role of MICU2 in regulating mitochondrial calcium uptake, mimicking the consequences of MICU2 knockout could provide valuable insights into tumor biology." (PMID 39466877, 2024). "Interestingly, we observed that cell cycle-related gene sets are frequently enriched in tumor samples with high MICU2 expression and tend to be less represented in tumor samples with a low MICU2 expression." (PMID 39466877, 2024). "Interestingly, even in the presence of activated CREB, there is an increase in the levels of MCU, MICU1, and MICU2 that significantly enhances tumor growth." (PMID 33114428, 2020). "Thus, the MICU2/MICU1 ratio is positively correlated to the aggressiveness of a CRC tumor, suggesting that the stoichiometry of the regulatory units of MCU complex may be critical for the tumor development." (PMID 39466877, 2024). "It has been reported that the promoters of other members can be recognized by CREB, and once bound to the promoter, the tumor highly expresses MCU, MICU1, and MICU2." (PMID 33114428, 2020). "The results showed two integration sites, one into the MICU2 and the other into CDH13 genes, the last being also found in the WES of patient’s primary tumor." (PMID 30760827, 2019). "To confirm the role of MICU2 in CRC tumor growth, we performed Ki67 staining on tumor sections." (PMID 39466877, 2024).
cancer (2 papers, 2024). A tumor composed of atypical neoplastic, often pleomorphic cells that invade other tissues. "Taken together, these results demonstrate that MICU2 expression is associated with several cancer cell properties." (PMID 39466877, 2024). "To further investigate the role of MICU2 in cancer, we investigated its role in the response to CRC chemotherapy treatment." (PMID 39466877, 2024). "These authors show that MICU2 ensures metabolic flexibility between anaerobic glycolysis and oxidative phosphorylation and regulates cancer cell proliferation." (PMID 39466877, 2024). "Overall, we report for the first time that MICU2 is a guardian of mitochondrial respiratory chain function and a pivotal element during the cancer metabolic switch from oxidative metabolism (oxidative phosphorylation [OXPHOS]) to glycolysis." (PMID 39466877, 2024). "Taken together, we propose that association between MICU1/MICU1, MICU2/MICU1, and MICU3/MICU1 implicated in MCU regulation shape the metabolic orientation of cancer cells." (PMID 39466877, 2024). "Based on the effect of MCU that has been described in cancer cells, we evaluated the role of MICU2 in cell motility (wound healing and spheroid migration assays)." (PMID 39466877, 2024). "Our results suggest that CRC cells with low MICU2 expression develop a preference for glycolysis to support cancer cell proliferation in a hypoxic environment." (PMID 39466877, 2024). "In particular, MICU2 is critical for cancer cell proliferation and the cell cycle." (PMID 39466877, 2024). "For the first time, we have demonstrated the central role of MICU2 in the balance between glycolysis and OXPHOS during cancer progression, and more specifically in CRC." (PMID 39466877, 2024). "In this study, we demonstrated that MICU2 is a guardian of mitochondrial OXPHOS and a pivotal element during the cancer metabolic switch from oxidative metabolism to glycolysis." (PMID 39466877, 2024). "Thus, we investigated the stoichiometry of MICU2/MICU1 and the molecular function of MICU2 in cancer cells by knocking down the MICU2 gene in CRC cells." (PMID 39466877, 2024).
MICU2 also shares sentences with these, for which no sentence is quoted: amyloid (1 paper); atherosclerosis (1); cardiovascular disease (1); cervical cancer (1); colorectal adenocarcinoma (1); diabetes (1); gastric cancer (1); lobular carcinoma (1); myopathy (1); renal clear cell carcinoma (1); triple-negative breast carcinoma (1); Ventricular hypertrophy (1).